IGKV2D-18 (immunoglobulin kappa variable 2D-18 (pseudogene))
Synonyms: A13; IGKV2D18
Gene: Immunoglobulin variable (V) pseudogene on chromosome 2 (90,052,581 to 90,053,372, forward strand). Ensembl gene ENSG00000254220.
Diseases named in the same sentence as IGKV2D-18 in open-access papers:
IGKV2D-18 is named in the same sentence as 1 disease in open-access papers, as found by Europe PMC text mining. Sharing a sentence is not in itself a finding about the gene and the disease.
IGKV2D-18 shares sentences with these, for which no sentence is quoted: cancer (1 paper).